CRP (C-reactive protein)
Diseases named in the same sentence as CRP in open-access papers (continued):
Sharing a sentence is not in itself a finding about the gene and the disease.
COVID-19 (continued). "Elevated levels of serum C-reactive protein (CRP) have been observed in patients with COVID-19 and used to assist with triage, diagnostics and prognostication." (PMID 33683344, 2021). "On the other hand, baricitinib, a high-affinity JAK1/2 inhibitor, has been shown to improve some clinical and laboratory parameters (including C-reactive protein levels) in a pilot study of COVID-19 cases." (PMID 33584343, 2021). "Most COVID-19 patients have exhibited elevated C-reactive protein, and a few of them have exhibited elevated CK." (PMID 34447759, 2021). "Significant differences in lymphocyte counts, D-dimer, CRP and lactate dehydrogenase were found between younger and older patients with COVID-19 (all P-values <0.05)." (PMID 33735325, 2021). "A study of 140 COVID-19 patients found elevated levels of IL-6 in 95, CRP in 91 and PCT in 8 patients, at admission." (PMID 33727641, 2021). "LUS was significantly correlated with COVID-19 biomarkers as C-reactive protein (CPR; p = 0.011), interleukin-6 (p = 0.013), and pro-adrenomedullin (p = 0.02), and inversely related to arterial oxygen saturation (p = 0.004)." (PMID 35127744, 2021). "Specifically, serum lipid levels decrease after acute COVID-19 onset and continue to decline in parallel with the increase of C-reactive protein concentration until the patient’s condition is resolved." (PMID 34944005, 2021). "In contrast the median ALT, AST, procalcitonin, CRP, fibrinogen D-dimer levels and sedimentation rate were significantly higher in the COVID-19 group." (PMID 33614298, 2021). "Other clinical studies also showed that treatment with anakinra reduced plasma CRP levels and improved respiratory function in COVID-19 cases." (PMID 34578460, 2021). "In contrast, D-dimer, CRP, and procalcitonin were significantly improved in survivors of the non-COVID-19 cohort after treatment." (PMID 34485324, 2021). "The machine learning models significantly outperformed the predictive scores derived from established COVID-19 risk factors such as age, BMI, Charlson comorbidity index (CCI), or molecular predictors such as CRP or IL-6 levels." (PMID 34139154, 2021). "The specific features of laboratory parameters in COVID-19 patients are lymphocytopenia, increased C-reactive protein (CRP) levels, and decreased liver function." (PMID 34814946, 2021). "To determine the levels of monocyte activation markers in convalescent COVID-19 individuals over time, we assessed the plasma levels of sCD14, CRP, sCD163 and sTF in the seven groups of COVID-19 individuals." (PMID 34642411, 2021). "Immunopathological changes, including relatively lower levels of WBCs and LYMs and markedly higher levels of CRP and inflammatory cytokines, are correlated with COVID-19 severity." (PMID 34415962, 2021). "Even if CRP is generally much higher in bacterial than in viral infections, patients with COVID-19 usually have markedly elevated levels." (PMID 34842822, 2021). "Median ALT, AST, procalcitonin, CRP, fibrinogen D-dimer levels and sedimentation rate were significantly higher in the COVID-19 group than the control group." (PMID 33614298, 2021). "Compared to laboratory assessments, COVID-19 patients in both cohorts had significantly lower lymphocyte count as well as higher C-reactive protein and D-dimer." (PMID 34357148, 2021). "The review focuses on syncytins and CRP expression in mental disorders and the case reports with mental symptoms in COVID-19 patients." (PMID 35059135, 2021). "In fact, COVID-19 is characterized by high levels of inflammatory markers, including C-reactive protein (CRP) and increased levels of inflammatory cytokines and chemokines." (PMID 33921297, 2021). "The median CRP amounts (145 vs. 20 mg/L,p < 0.001), as well as the D-dimers (4,581 vs. 752 ng/mL,p < 0.01), were higher in the COVID-19 group." (PMID 34568743, 2021).
COVID-19 (continued). "Increases in lactate dehydrogenase, C-reactive protein (CRP), D-dimer, ferritin and interleukin-6 (IL-6) are common laboratory findings in patients with COVID-19." (PMID 33670475, 2021). "The baseline laboratory results between the two groups are given in; c-reactive protein and white cell count were higher in the COVID-19 positive group with a relative lymphopaenia." (PMID 38603069, 2021). "Lymphopenia, elevated level of d-dimer, hs-CTnI and hs-CRP predicted clinical outcomes of young adults with severe COVID-19." (PMID 33407543, 2021). "Serum LDL-C levels of COVID-19 patients was negatively correlated with CRP level (r = −0.165, P = 0.026), but positively correlated with lymphocyte count (r = 0.138, P = 0.047)." (PMID 34124081, 2021). "In COVID-19 patients higher LDH, CRP, IL-6, and D-dimer values were associated with longer lag-time triggered by TF." (PMID 33833254, 2021). "For inflammation indicators, including ESR, CRP and IL-6, COVID-19 all patients with COVID-19 infection showed a significantly elevated state (the IL-6 level in patients with mild cases was within the normal range)." (PMID 34222271, 2021). "Inflammatory markers in COVID-19 patients in our study, including CRP, ESR, and LDH, were inconsistent with the findings of 2 meta-analyses." (PMID 34081600, 2021). "Although only four studies are included that investigated androgens in patients with COVID-19, the results of this review suggest that testosterone may be reduced in male patients with COVID-19 compared to controls, and this is negatively associated with CRP as a systematic marker of inflammation." (PMID 34552795, 2021). "CRP apheresis has been used once before in a COVID-19 patient, who was already ventilated and progressed far during the deleterious course of SARS-CoV-2 infection." (PMID 34408751, 2021). "COVID-19 patients with a higher serum level of CRP at admission (3-5 days post-SARS-CoV-2 infection when symptoms appear), which continues for 2-3 weeks, have an additional risk for poor prognosis." (PMID 35126355, 2021). "Therefore, we speculate that IL-2R, IL-6 and CRP are associated with the severity of COVID-19." (PMID 33542448, 2021). "Consistent with such an important role for inflammation in COVID-19, is the finding that both IL-6 and CRP are strong markers of COVID-19 disease activity." (PMID 33692801, 2021). "The full model included age, male sex, severe COVID-19, CRP, eGFR, clinical frailty score, and the presence of one or more major comorbidity." (PMID 33557238, 2021). "It has been noted that decreased levels of erythrocytes and lymphocytes as well as increased levels of alanine aminotransferase and CRP were the main predictors of the severe course of COVID-19 in pregnant women." (PMID 34439868, 2021). "The effects of these therapies on PCT and CRP levels in critically ill COVID-19 patients are largely unclear, but were previously assessed in non-COVID-19 patients." (PMID 34353339, 2021). "Based on these criteria, we selected seven key variables: age, male sex, severe COVID-19, CRP, estimated glomerular filtration rate (eGFR), clinical frailty score, and the presence of one or more major comorbidity." (PMID 33557238, 2021). "Serum CRP levels and pO2 were also considerably higher patients with higher severity and can be used along with other factors to predict severe disease in COVID-19 patients." (PMID 33888747, 2021). "There was a linear trend between COVID-19 severity and the number of laboratory biomarkers of lymphopenia, inflammation [i.e., CRP, procalcitonin], and organ function measures [i.e., AST, ALT or creatinine) on admission in both cohorts." (PMID 34660338, 2021). "Elderly patients also had significantly higher titres of neutralizing antibodies after COVID-19 and higher serum level of CRP at the time of hospital discharge." (PMID 34640355, 2021). "One small study showed lower plasma CRP and IL-6 levels and lower mortality in COVID-19 patients who were treated with siltuximab." (PMID 34578460, 2021).
COVID-19 (continued). "In line with this evidence, we found that the level of several soluble proinflammatory markers were increased (e.g., CRP, ferritin, IP-10, and IL-6) in the >65 years compared to <65 years COVID-19 patients." (PMID 34682920, 2021). "D-dimer and CRP levels were frequently measured in patients with COVID-19 admitted during the first peak of the pandemic, with its worse altered values more frequently observed during the first week of hospital stay." (PMID 34909913, 2021). "Levels of C-reactive protein, a known marker of disease severity in COVID-19, were also reduced following rhDNase treatment." (PMID 34139362, 2021). "Nevertheless, this is, to our knowledge, the first study to assess the predictive value of PCT and CRP for detection of secondary infection after the introduction of dexamethasone and tocilizumab treatment in critically ill COVID-19 patients." (PMID 34353339, 2021). "Overall, in obstetric patients hospitalized with COVID-19, C reactive protein is the inflammatory biomarker that better mirrors the course of the disease whereas D-dimer or ferritin are not reliable predictors of poor outcome." (PMID 34172816, 2021). "In severe COVID-19, studies showed a pronounced elevation of CRP, indicating an increased systemic inflammatory response, and a decrease in lymphocytes, indicating a disruption of the immune response by the virus." (PMID 34945746, 2021). "Our results showed lower total lymphocyte count and higher level of CRP in patients with severe COVID-19." (PMID 34220524, 2021). "In patients with a severe course of COVID-19, in addition to hypercytokinemia, high levels of ferritin, CRP, and D-dimer were also recorded, which indicated the development of severe MAS inflammation and fibrinolysis." (PMID 34359987, 2021). "Individuals in cohort one with acute COVID-19 had coagulopathy (with increased D-Dimer and fibrinogen), a marked pro-inflammatory response (elevated CRP, IL-6, TNF-α, IL-8 and IL-1β) and lymphopenia, with an increase in the neutrophil: lymphocyte ratio." (PMID 34025675, 2021). "Our results showed high CRP in children with COVID-19 but, adults have a much higher prevalence of increased CRP than children, suggesting a much milder immunological response in children and less immune damage." (PMID 33765980, 2021). "Many researchers suggested that early COVID-19 cases generally have normal or decreased leukocyte and reduced lymphocyte, and most patients have increased hs-CRP and normal PCT." (PMID 34122620, 2021). "Elevated levels of C-reactive protein (CRP) and Procalcitonin (PCT) have been associated with severe COVID-19, which suggests that these can be used as biomarkers for disease prognosis." (PMID 34362074, 2021). "Multivariate analysis showed that high NEFAs, low ApoE and low HDL cholesterol concentrations are significantly associated with COVID-19 status, independently of body mass index, baseline severity (SOFA score) and acute phase response (CRP level)." (PMID 34031519, 2021). "A risk score formula was preliminarily built to predict the probability of COVID-19 as follows: Logit (P = COVID-19) = 10.104 + 1.915 × fever + 1.753×chest CT + (−2.508) × CRP + (−0.8)×PCT + (−1.836) × WBC." (PMID 33996842, 2021). "A number of studies have reported that increased levels of inflammatory mediators such as CRP, IL-6, procalcitonin, and serum ferritin were commonly seen among patients with COVID-19, especially in critical or death cases." (PMID 33859687, 2021). "CRP was recently shown to correlate with the extent of lung pathology and disease severity in COVID-19 patients." (PMID 34178545, 2021). "Elevated lactate dehydrogenase, C-reactive protein, and interleukin-6 levels are other common laboratory findings among hospitalized patients with COVID-19." (PMID 34208017, 2021).
COVID-19 (continued). "In accordance with our results, a meta-analysis of biomarker levels before and after administration of tocilizumab in COVID-19 patients showed a reduction of CRP and a -non statistically significant-reduction of PCT." (PMID 34353339, 2021). "The mean plasma levels of the inflammation markers CRP, procalcitonin, and ferritin were elevated above the normal range in the COVID-19 patient group." (PMID 34377464, 2021). "Examination of COVID-19 patients demonstrated that heart rate, respiratory rate, body temperature, C-reactive protein levels, as well as lung damage increased significantly with COVID-19 severity, whereas SpO2 decreased gradually." (PMID 33920813, 2021). "Our findings indicated that C-reactive protein level, serum ferritin, and troponin-I were autonomous predictors of severity in COVID-19 cases." (PMID 33628256, 2021). "The same association was found in another study that also highlighted a link between 25(OH)D levels and lymphocyte percentage count and C-reactive protein (CRP) levels in COVID-19 patients." (PMID 34576172, 2021). "ApoA-1 and HDL levels were shown to be negatively correlated with CRP and IL-6 levels in patients with COVID-19, suggesting that the increased inflammatory response related to reduced HDL levels is one of the pathogenic mechanisms of COVID-19." (PMID 34335279, 2021). "As recently suggested for vitamin C and glutathione, monitoring of OSS should be implemented in COVID-19 critically ill patients, including vitamin C, GSH in association with PSH, and, finally, ROOH in association with the Cu/Zn ratio and CRP." (PMID 33562403, 2021). "Our overall data are in accordance with previous reports in which male sex, multiple comorbidities, elevated CRP and low lymphocyte count were observed in the majority of COVID-19 deaths." (PMID 33838684, 2021). "CRP in severe COVID-19 patients increased significantly at the initial stage, before computed tomography findings." (PMID 34439469, 2021). "Elevated levels of inflammatory factors such as IL-6 and CRP were observed in the paediatric patients with COVID-19." (PMID 34697118, 2021). "The present study showed upward trends in inflammatory indexes along with the exacerbation of COVID-19, such as C-reactive protein and interleukin levels." (PMID 34034769, 2021). "Laboratory examination showed that some patients with COVID-19 had slightly elevated C-reactive protein (2/8,>5.0 mg/L)." (PMID 33441152, 2021). "When referring to the initial COVID-19 assessment, the hospitalized patient group had significantly more severe pulmonary injuries, higher levels of CRP, lower oxygen saturation, and more accelerated heart rates." (PMID 34827455, 2021). "Coffee consumption favorably correlates with inflammatory biomarkers such as CRP, interleukin-6 (IL-6), and tumor necrosis factor α (TNF-α), which are also associated with COVID-19 severity and mortality." (PMID 34203027, 2021). "In our cohort, we only found an elevation of CRP > 29 mg/L in almost two-third of patients in a complicated clinical stage at time of COVID-19 diagnosis." (PMID 33001409, 2021). "Currently, multiple biomarkers in COVID-19 have been identified, such as leukocytes, C-reactive protein (CRP), procalcitonin (PCT), lactate dehydrogenase (LDH), ferritin, and cytokines (IL-2R, IL-6, IL-8, IL-10, and TNF-α)." (PMID 34573984, 2021). "In COVID-19 patients receiving prophylactic anticoagulation, elevated levels of C-reactive protein (OR 2.7) and D-dimer (OR 6.7), as well as thrombocytosis (OR 3.5) at admission were predictive of coagulation-associated complications during hospitalization." (PMID 34441957, 2021). "Higher levels of C-reactive protein (CRP), leukocytes, and cytokines are associated with both CAD and severe COVID-19 patients." (PMID 34071557, 2021). "We also found that the levels of pro-inflammatory cytokines and infection-related biomarkers were higher in severe COVID-19 patients with cancer, including procalcitonin, CRP and IL-6." (PMID 34353293, 2021).
COVID-19 (continued). "COVID-19 patients showed high levels of C-reactive protein (CRP), lactate dehydrogenase (LDH), and α-hydroxybutyrate dehydrogenase (HBDH) as a result of inflammation-inducing GI or liver injury." (PMID 34777871, 2021). "Based on the present study’s findings, the laboratory profile of pregnant women with COVID-19 is similar to that of the control group except for C-reactive protein concentration, ALT, and AST." (PMID 34149282, 2021). "Median initial C-reactive protein (CRP) was 4.6 mg/dL (IQR 1.4–11.1) in total COVID-19 patients compared to 15.9 mg/dL (IQR 11.2–23.1) in total MIS-C patients." (PMID 33627147, 2021). "Many scholars found that changes in blood, high-sensitivity C-reactive protein (hs-CRP), and d-dimer, combined with a patient’s age and medical complications, had distinct instructive value for critical COVID-19 patient prognosis." (PMID 33854118, 2021). "We aimed to investigate the association between several biomarkers, including serum C-reactive protein (CRP), procalcitonin (PCT), and serum ferritin, and COVID-19 severity." (PMID 34185186, 2021). "Laboratory tests revealed lymphopenia and elevated C-reactive protein (CRP), both typical biomarkers of COVID-19." (PMID 33752743, 2021). "The mean CRP between 97 COVID-19 patients that were dead, was 85.82 mg/l (CI = [53.08–118.56], P < 0.001), while the mean of CRP between 973 improved patients was 32.99 mg/l (CI = [18.94–47.03], P = 0.007)." (PMID 33726761, 2021). "The severity of COVID-19, duration of RNA shedding and the CRP levels were identified as potential predictors of IgG levels." (PMID 34804188, 2021). "This is consistent with this research which showed that serum CRP levels were significantly higher in the cohort of deceased COVID-19 patients." (PMID 34904053, 2021). "The results show that the KL-6 and CRP are significantly higher in COVID-19 patients with pulmonary fibrosis compared with patients without pulmonary fibrosis." (PMID 33907520, 2021). "As reported by researchers, CRP levels are positively correlated with the severity of COVID-19 and lung lesions." (PMID 35154611, 2021). "Even a recent meta-analysis revealed that nearly 50% of COVID-19 patients had significant elevations of CRP." (PMID 33988463, 2021). "Subjects suffering from COVID-19 express a range of similar symptoms such as lymphopenia, hypercoagulability, and cytokine storm (elevation in IL-6, CRP, TNF, MCP1, IL-1β levels, and others)." (PMID 34680053, 2021). "The most frequently reported predictors for severe patients with COVID-19 in other researches included age, comorbidities, vital signs, image features, sex, lymphocyte count, and C reactive protein." (PMID 34620102, 2021). "In our cohort, hospitalized CF carriers develop indeed a form of COVID-19 more likely characterized by acute respiratory distress syndrome (PaO2/FiO2 ratio ≤ 250 mmHg), high inflammatory response (CRP ≥ 20 mg/dL), and, for some of them hyperlipasemia." (PMID 34203982, 2021). "CRP is a well-known biomarker of inflammation and is found elevated in 60.7% of patients with COVID-19." (PMID 33633875, 2021). "Patients with severe COVID-19 had lower lymphocyte count and higher median values of transaminases, lactate dehydrogenase, C-reactive protein, procalcitonin, D-dimer, and interleukin-6 than patients with mild-to-moderate COVID-19 (all P < 0.001)." (PMID 33481096, 2021). "Significant elevation of acute phase reactants such as CRP, ferritin and D-dimer have been shown to be good predictors of poor survival in COVID-19 patients." (PMID 33672040, 2021). "These variables, along with a decrease in T cells and a high level of CRP, can aid in the early detection of COVID-19 clinical development." (PMID 34514172, 2021). "Among them, we noticed the increased levels of C-reactive protein (CRP), d-dimer, and ferritin showed good indicative value to evaluate the severity of COVID-19." (PMID 34314447, 2021).